SNORD36A (small nucleolar RNA, C/D box 36A)
Synonyms: U36a; RNU36A
Gene: Small nucleolar RNA gene on chromosome 9 (133,350,456 to 133,350,528, forward strand). Ensembl gene ENSG00000199744.
Gene Ontology:
Biological process: RNA processing
Cellular component: nucleolus
Homologues: Orthologues: chimpanzee SNORD36 (100% identical), macaque SNORD36 (97% identical), guinea pig SNORD36 (90% identical), pig SNORD36 (88% identical), rat LOC120101982 (85% identical), mouse Gm24134 (84% identical), dog SNORD36 (81% identical). Paralogues in human: SNORD36 (71% identical), SNORD36B (70% identical), SNORD36C (56% identical).